FOXP3 (forkhead box P3)
Diseases named in the same sentence as FOXP3 in open-access papers (continued):
Sharing a sentence is not in itself a finding about the gene and the disease.
tumor (continued). "Within the epithelial compartment, we found highly statistically significant associations with survival for intraepithelial CD8+ T cells (including both FoxP3– and FoxP3+ subsets), PD-1+ immune cells, CD68–PD-L1+ cells (presumptive PD-L1+ tumor cells), and B cells." (PMID 39470729, 2024). "Conversely, the constitutive absence of CD11chi DCs enhanced the proportion of CD4+Foxp3+RORγt+ Treg cells in lymphoid tissues under homeostatic and tumor-bearing conditions." (PMID 39206204, 2024). "High grade tumors had a significantly higher infiltrate of FoxP3+ cells (p = 0.02), CD68+ cells (p = 0.01), CD163+ cells (p = 0.01), LAG3+ cells (p = 0.01), PD1+ cells (p = 0.01) and TIM3+ cells (p = 0.03) when compared with low grade tumours." (PMID 38691575, 2024). "Regarding the tumor infiltrating lymphocytes (TILs) compartment, PeptiCRAd and PeptiCRAd+ DAC, despite a lower CD4+ T cell infiltration, showed a reduced percentage of intratumoral Tregs (CD25+, FOXP3+)." (PMID 38596301, 2024). "Even prior to the identification of the transcription factor Foxp3 as the canonical driver of Tregs, seminal work found that depletion of CD25+ T cells (a subset of which are Tregs) before tumor implantation can lead to enhanced antitumor immune responses and eventual spontaneous tumor rejection." (PMID 38429261, 2024). "TIL markers such as CD3, CD4, CD8, and FOXP3 can predict the survival outcomes of OSCC patients, but do not serve as independent prognostic markers as found with conventional factors (i.e. nodal status, tumor differentiation and PNI)." (PMID 38926643, 2024). "FOXP3+ Tregs, a subset of CD4 + T cells, are known for their immunosuppressive roles in the TME, often inhibiting the activity of effector T cells and promoting tumor growth." (PMID 38331898, 2024). "CD4+ T cells were comprehensively found in greater proportions in tumor populations, with CD4+ central memory (Tcm) (Diff = 7.2%, p = 0.031), FOXP3+ T regulatory (Treg) (Diff = 7.6%, p = 0.035), Naive CD4+ (Diff = 13.2%, p = 0.0021), and T helper 2 (Th2) (Diff = 3.6%, p = 0.0059) all enriched." (PMID 39075108, 2024). "Furthermore, based on mIF analysis, the PCR group showed higher cell densities of CD8+, PD-L1+, and CD8+PD-L1+ in the tumor region, while showing lower cell densities of CD3+Foxp3+, Foxp3+, and CD163+." (PMID 38887237, 2024). "In addition, Ad-GFP-WT or -GFP mutant resulted in an equivalent reduction in tumor burden compared with control vaccination, although mice were somewhat protected by the GFP in Foxp3 cells." (PMID 38592453, 2024). "When compared to GC tumor tissues, the CD8/Foxp3 ratio in GC paracancerous tissues is much greater, and the elevated expression of PD-L1 could signal a bad prognosis for GC patients." (PMID 38919615, 2024). "In the context of NSCLC, the presence of tumor-infiltrating Tregs (FOXP3+ Tregs) can have both positive and negative effects on the immune response." (PMID 38674427, 2024). "Blimp1-deficient Tfr cells exhibit impaired inhibitory activity and reduced production of Foxp3, CTLA-4, and other cytokines, contributing to inhibit interactions with Tfh cells and B cells and promote anti-tumor immunity, and these destabilized Tfr cells convert to Tfh-like cells." (PMID 39227959, 2024). "Additionally, they demonstrated FoxP3 suppressed the proliferation and invasion of HCC cells in vitro and reduced tumor growth in vivo." (PMID 39073490, 2024). "We found that infiltration of CD4+ T cells, as well as Foxp3+CD4+ T cells in tumour tissue, gradually increased from no to high PD-L1 IC; this increase was primarily driven by the high PD-L1 expression group." (PMID 38541208, 2024).
tumor (continued). "However, tumor-bearing WT mice and CD11c:DTA mice showed comparable accumulations of CD4+Foxp3+ Treg cells and CD4+Foxp3+RORγt+ Treg cells in tumor tissues." (PMID 39206204, 2024). "MMP12 might promote Foxp3+Treg infiltration in tumor tissue; TLR4 might obliquely attract Foxp3+Treg to the tumor location by interacting with TGF-β and macrophages." (PMID 38919615, 2024). "Our findings showed that the expression of CD8 was significantly downregulated in subcutaneous tumor tissues with Fh1 knockdown, while FOXP3 and PD-L1 were not significantly changed." (PMID 38398104, 2024). "Expression of Foxp3 in relation to T cells and cancer cells in the CRC tumor microenvironment." (PMID 38919615, 2024). "In tumor microenvironment, CD4+ CD25low T cells and CD4+ CD25- T cells may get induced for FOXP3 expression and converted to CD4+ CD25+ Tregs." (PMID 38571964, 2024). "Based on the impact of CAF-S1 fibroblasts on immunosuppression, we next investigated Tumor infiltrating lymphocyte (TIL) density and localization before and after chemotherapy in HGSOC patients by performing CD3, CD8 and FOXP3 IHC staining in the Retrospective Curie 1 cohort." (PMID 38346978, 2024). "In addition, IL-10 induces the overexpression of Foxp3 in CD4+ T cells, increasing the number of Tregs in the tumor." (PMID 39085255, 2024). "Immune killing by Foxp3+ regulatory T cells is regulated by negative feedback, and an excessive presence of regulatory T cells inhibits immune killing while promoting tumor escape." (PMID 38887237, 2024). "Besides, the combined assessment of reduced CD8+/FOXP3+ TIL density and PD-L1 overexpression is proposed as a potential indicator for tumor differentiation and LN status in ESCC." (PMID 39399490, 2024). "Tumor immune status was evaluated using immunohistochemical staining to identify CD3+, CD8+ and FOXP3+ tumor-infiltrating lymphocytes (TILs), and the relationship of NLR, with clinicopathologic characteristics including 5-year overall survival (OS), and the tumor immune status was investigated." (PMID 38704243, 2024). "Treatment of tumor-bearing animals with OX40/CD137 bispecific agonists reprograms Tregs into both fragile Foxp3+ IFNγ+ Tregs with decreased suppressive function and lineage-instable Foxp3− IFNγ+ ex-Tregs." (PMID 38995700, 2024). "Data from the tumour epithelial area for FoxP3+ T regulatory cells and CD20+ B cells was not further analysed since these immune cells were rarely present within this compartment." (PMID 38040818, 2024). "However, when stratifying per cell type, FoxP3+ regulatory T cells (Tregs) were significantly less frequent in CNA-quiet OCSCC, explained by a lower fraction in the tumor center." (PMID 39428388, 2024). "For a comprehensive view of the tumor-infiltrating T cell landscape, the markers CD3, CD8, CD4, Programmed Cell Death Protein (PD)-1, granzyme B (GrzB) and Forkhead-Box-Protein P3 (FoxP3) were employed in addition to 4′,6-Diamidin-2-phenylindol (DAPI) nuclear staining." (PMID 38631706, 2024). "Post-treatment, the tumor microenvironment showed immunomodulatory changes, including altered macrophage infiltration and significant gene expression changes related to inflammation and immune response, such as IDO1, IL-6, TNF, CD209, and FOXP3." (PMID 39765586, 2024). "Tumor biopsies from patients receiving eribulin treatment were collected and analyzed for the expression of immune markers including PD-L1, PD-L2, CD8 and the Treg marker FOXP3." (PMID 39050852, 2024). "Additionally, the expression levels of FOXP3, FOXO3, FOXO1, FOXA2, and FOXM1 were found to be elevated in GBM tissues from the TCGA database compared to non-tumor brain tissues, while the level of FOXQ1 was reduced." (PMID 38561331, 2024). "While high Zn intake increased the tumor growth in the control group, high Zn intake failed to increase tumor mass in DT-induced Foxp3+ Treg-ablated mice." (PMID 39247196, 2024).
tumor (continued). "The purpose of this study was to investigate the effects of T. gondii excretory‐secretory antigens (ESA) on CD4 + CD25+ Foxp3+ Treg cells in mice with LLC and to determine whether T. gondii ESA inhibits tumor growth." (PMID 38109851, 2024). "Tregs, characterized by CD4+/CD25+/FoxP3+ expression, can inhibit CD8+ T cell cytotoxicity by secreting immunosuppressive cytokines such as interleukin-10 (IL-10) and transforming growth factor-beta (TGF-β), thereby facilitating tumor immune evasion." (PMID 39769460, 2024). "Our results showed the potential regulation of NONHSAT136151 by FOXP3, suggesting that NONHSAT136151 may be a novel pathway for FOXP3 to be involved in tumour microenvironment regulation." (PMID 38041531, 2024). "In addition, TREM-1 + TAMs also respond to hypoxic conditions and tumor metabolites through the ERK/NF-κβ pathway, resulting in an increase in CCR6 + Foxp3 + Tregs, which promotes tumor immunosuppression and creates resistance to PD-L1-targeted therapies." (PMID 39068459, 2024). "Tregs, characterized by FOXP3 expression, are recruited to CRC sites via chemokine signaling and exert immunosuppressive functions by suppressing effector T cell responses and hindering anti-tumor immune surveillance." (PMID 38289597, 2024). "Immune cell infiltration was further explored in the U-CAN validation cohort using multiplex immunohistochemistry and multispectral imaging to detect cytotoxic T cells (CD8+), T helper 1 cells (T-bet+), T regulatory cells (FoxP3+), B cells (CD20+), and macrophages (CD68+) at the tumour front." (PMID 39613865, 2024). "Tumor tissues analysis for immune infiltration components revealed that PD and PR patients had higher levels of regulatory immunosuppressive T-cells (CD4+, FOXP3+) compared to CR patients." (PMID 39632825, 2024). "FOXP3 may act as a coactivator to facilitate key signaling pathways, such as WNT, inducing EMT and tumor growth and metastasis in NSCLC." (PMID 38674427, 2024). "Fewer CD8+ T cells and more Foxp3+ Tregs were present in the high LLT1TC group (tumor front: p = 0.071 and tumor center: p = 0.637), suggesting that LLT1TC high patients might have an immunosuppressive TME in situ." (PMID 38502058, 2024). "Furthermore, Foxp3+ CD25+ CD4+ T cells (Treg), defined as a suppressor in aberrant immune response, also play a role in the suppression of anti-tumor immunity." (PMID 38164171, 2024). "Although Treg cells in CHL are mainly of thymic origin (FOXP3 positive), FOXP3 negative Treg cells also exist in the tumor microenvironment." (PMID 39200145, 2024). "We noted an increase in the densities of CD4+T and CD8+ T cells in the tumor of the Pa + mAb group, while the density of FoxP3+ cells showed no significant change." (PMID 38961326, 2024). "They noted that SUVmax significantly correlated with the CD8/forkhead box P3 (FOXP3) ratio, an immune-functional marker of tumor-infiltrating lymphocytes (TILs), which are major components of TIME and are substantially related to tumor progression and response to chemotherapy in BC." (PMID 39110196, 2024). "Notably, analysis of TLSs revealed that not only CD20+ B cells were present in the TLSs of the tumor, but they also colocalized with CD4+, CD8+, and FOXP3+ T cells." (PMID 39473903, 2024). "Furthermore, we observed an unexpected connection between the distance from CD3+FoxP3+ to CD3+CD8+GrB+ T cell and the distances among other immune cells or immune cells to tumor cells." (PMID 38375478, 2024). "The single non-Vδ1Vδ2 cluster present in the tumours had a high expression of CD45RO and Fas (CD95), and also a higher expression than most other clusters of several proteins expressed in activated cells, such as ICOS (CD254), OX-40 (CD134), CD25, and FoxP3." (PMID 38953978, 2024). "Additionally, B-MFs contributed significantly to tumor progression by adopting immunosuppressive phenotypes and promoting cancer growth through the suppression of anti-tumor IFNγ+ CD4+ T cells and the induction of FoxP3+ Tregs." (PMID 39457693, 2024).
tumor (continued). "Conversely, Foxp3 expression by cytotoxic CD8+ T cells might aid a metabolic shift and survival, similar to that seen in the tumour microenvironment." (PMID 39101538, 2024). "Additionally, a strong link between sPD-L1 and CD4+CD25+Foxp3+ regulatory T cells in BCR cases was observed, indicating sPD-L1’s systemic impact on tumor progression." (PMID 39055716, 2024). "As aTreg cells are thought to be the main effectors of suppression among human FOXP3+ Treg subsets, their expansion in patients with advanced CLL could support tumour-immune evasion by suppressing antitumour T cell responses." (PMID 39335199, 2024). "Additionally, we partially revealed the regulation of NONHSAT136151 expression by FOXP3, indicating a potential role of NONHSAT136151 in contributing to the tumour microenvironment." (PMID 38041531, 2024). "In our study, the FOXP3 expression and Tregs were high in low-ACADM group, implying that ACADM might influence the Tregs infiltration in the tumor microenvironment and the prognosis of ccRCC patients." (PMID 38664460, 2024). "Furthermore, researchers have discovered that the adaptive metabolism of tumor-infiltrating TI-Tregs in the TME could serve as a potential target for cancer therapy due to their ability to enhance ATP production under hypoxic conditions through FOXP3-induced OXPHOS." (PMID 39144146, 2024). "The tumor-infiltrating lymphocytes (TILs) in the central and peripheral regions of the tumors were analyzed separately using markers including CD20, CD3, CD68, CD8, CD4, CD163 and FOXP3." (PMID 39198311, 2024). "In addition, TIL density takes into account other cell subtypes (CD4+, FOXP3) besides CD8+, thus providing a more comprehensive description of the conditions and immune interactions in the tumor microenvironment that contribute to the overall results." (PMID 38638854, 2024). "Accordingly, we found that a higher fraction of CD8+ T cells in NR patients are closer to TAMs and FoxP3+ cells, making us to assume that macrophages and Treg act as immunosuppressive populations limiting CTL anti-tumor activity and patient response to ONCOFID-P-BTM." (PMID 38600583, 2024). "We hypothesize that extended ICI treatment achieves a tumor microenvironment in which CD4/CD8 TIL levels are high and FOXP3 levels are low, contributing to the downregulation of VEGF signaling." (PMID 38013668, 2024). "CD4 + FOXP3 + Treg cells also demonstrated extensive communication with other cells in LCC, but there was relatively limited interaction between immune cells and tumor cells." (PMID 39267963, 2024). "High PD-L1+ lymphocyte infiltration in tumour stroma was more common in tumours with higher CD4+ T cell infiltration in islets and stroma, Foxp3+CD4+ T cell infiltration in islets and lover M1 macrophage infiltration in the stroma (p = 0.034, p = 0.034, p = 0.005 and p = 0.034 respectively)." (PMID 39409156, 2024). "These structures could be visible by staining, including panel I: CD8+ T cells, CD4+ T cells, PD-1+ cells, PD-L1+ cells, Foxp3+ regulatory T cells; and panel II: CD19+ B cells, CD56+ NK cells, CD68+ macrophages, CD163+ M2 macrophages, cytokeratin+ tumor cells." (PMID 38637495, 2024). "As a consequence, upregulation of IDO1 expression in tumor cells, programmed cell death 1 (PD-1) in CD8+ T cells and forkhead box P3 (FOXP3) in CD4+ T cells occur, overall impairing CD8+ T cells proliferation and promoting the conversion of CD4+ T cells to Tregs." (PMID 37122718, 2023). "To explore whether the immune cell subsets of tumor tissues with high expression of ICOSLGTCs in OSCC patients changed, we determined the ICOSLG, CD4, CD8, CD19, CD68 and Foxp3 level of tumor centers and infiltration fronts in serial sections." (PMID 37842091, 2023). "Some subgroups exhibit tumor-suppressive effects (notably effector CD3+, cytotoxic CD8+ and memory CD445RO+), while some other subgroups exhibit tumor-supportive effects (regulatory FoxP3+ and immune tolerance PD-1+)." (PMID 37583899, 2023).
tumor (continued). "These increased tumor-infiltrating lymphocytes include CD4+ T cells, Foxp3+ Treg cells." (PMID 37143538, 2023). "Furthermore, anti-CTLA-4 makes FOXP3+CD4+ Tregs alleviate their immunosuppressive activities and contribute to anti-tumor immune response." (PMID 36721212, 2023). "FoxP3+ T regulatory (Treg) cells predominated and there was little CD8+ infiltration in solid tumors of both humans and mice that express specific Fas ligands in the tumor vasculature." (PMID 37056346, 2023). "T cells in the normal liver parenchyma distal to the tumour were generally not found to express FoxP3." (PMID 39516397, 2023). "In addition, immune cells of the tumor microenvironment (CD4, CD8, FoxP3) were to be evaluated for prognostic suitability and a particular focus should be on the prediction of LNM." (PMID 37932810, 2023). "In the TCGA-UCEC dataset, APOBEC3G, CUL4B, SCML2, TSPYL5, and ZBTB16 were significantly downregulated in tumor samples, whereas FOXP3, HJURP, HMGB3, and RAC3 were significantly upregulated in tumor samples, which was generally consistent with the result observed in GSE17025." (PMID 36936912, 2023). "The percentage of splenic FOXP3+ Tregs was significantly higher in mice bearing large tumors than in mice bearing small tumors, regardless of the time elapsed since tumor inoculation, and always higher than that in control mice." (PMID 37990034, 2023). "The incubation of EA.hy.926 cells with CM or with P60 did not affect the migratory capacity of EA.Hy.926 cells, suggesting that Foxp3 does not participate in the modulation of the tumor angiogenic process." (PMID 37766222, 2023). "As expected, FOXP3 predominantly activated in Treg and CD4+ Tex, and within each tumor, whether for PT or BM, the percentage of them showed significant correlation (Pearson correlation, R = 0.45, p = 0.005)." (PMID 36671569, 2023). "Moreover, a stronger interaction was found between the tumor stem cell subpopulation and exhausted CD8+ T cells with FOXP3+ using multiple immunofluorescence techniques." (PMID 38066053, 2023). "On day 15 of treatment, we observed a significant upregulation of tumour immunogenicity markers (MHCI and PD-L1), significant increase in the proportion of tumour-infiltrating CD8+ and CD4+/FOXP3- T effector cells as well as the production of IFNγ by CD4+ T cells." (PMID 37582853, 2023). "Gan mice treated with a high-fat diet with GO-Y022 showed shrinkage of the tumor size, but the number of Foxp3+ Tregs per tumor area (mm3) was not different from that of the control mice." (PMID 36814928, 2023). "The tumor diameter and concentrations of CD8+, FOXP3+, HLA-DR+ and CD31+ were no longer associated with poor survival rates." (PMID 36765559, 2023). "Also, it was observed that the presence of FoxP3+ and CD25+ regulatory tumor-infiltrated T-cells was higher in persistent and precancerous lesions than in uterine cervical cancer." (PMID 37375112, 2023). "Furthermore, we noted that the proportions of tumor-reactive CD8 + and CD4 + FoxP3- T-cells were similar, except for MM, which had significantly fewer tumor-reactive CD4 + FoxP3- T-cells than in NSCLC." (PMID 38057799, 2023). "Having established a role for DKK1 in promoting tumour immune modulation and defined the relationship between DKK1 levels and FOXP3+ cells in a cohort of human samples, we next wanted to test whether DKK1 inhibition was effective at reducing iCCA growth." (PMID 35924447, 2023). "Combination therapy showed a further reduction in tumor burden compared with monotherapies or untreated control, inducing the highest numbers of intratumoral CD3 + and CD8 + T cells and the lowest numbers of Foxp3 + and BrdU-positive tumor cells." (PMID 36653774, 2023). "AhR activation by kynurenines could induce the transcription factor FoxP3, promoting the inhibition of cytotoxic effector T cells, such as CD8+ T cells and NK cells, thus allowing tumor cells to escape destruction." (PMID 36986469, 2023).